DEFB106B (defensin beta 106B)
Description:
Has antibacterial activity. Acts as a ligand for C-C chemokine receptor CCR2.
Synonyms: BD-6; DEFB-6
Gene: Protein-coding gene on chromosome 8 (7,482,504 to 7,486,400, reverse strand). Ensembl gene ENSG00000187082.
Subcellular location: Secreted; Membrane
Pathways (Reactome):
Immune System: Beta defensins; Defensins
Gene Ontology:
Molecular function: CCR2 chemokine receptor binding; heparin binding; lipopolysaccharide binding; protein binding
Biological process: antifungal innate immune response; defense response to Gram-negative bacterium; defense response to Gram-positive bacterium; innate immune response
Cellular component: membrane; microvesicle; nucleus; extracellular region
Homologues: Orthologues: chimpanzee DEFB106A (100% identical). Paralogues in human: DEFB106A (100% identical).